PPARG (peroxisome proliferator activated receptor gamma)
Diseases named in the same sentence as PPARG in open-access papers (continued):
Sharing a sentence is not in itself a finding about the gene and the disease.
brain tumor (11 papers, 2008 to 2023). "The induction of growth arrest and apoptosis by PPARγ agonists was associated with the expression of PPARγ and inhibition of Tyk2-Stat3 signalling pathway in BTSCs, further suggesting the use of PPARγ agonists in the treatment of brain tumours." (PMID 19018263, 2008). "Although the precise molecular basis of the antineoplastic mechanisms of PPARγ agonists is not fully understood, our findings suggest that the clinically used PPARγ agonists may offer new therapies to target BTSCs for the treatment of brain tumours in patients." (PMID 19018263, 2008). "For example, PPARγ maintains the stemness in ERBB2-positvie breast CSCs, in contrast, PPARγ agonists inhibit the expansion of brain tumor stem cells." (PMID 33482915, 2021). "Chearwae and Bright reported that PPARγ agonists inhibited growth and expression of brain tumor stem cells by inhibition of EGF/bFGF signaling through Tyk2-Stat3 pathway and the expression of PPARγ." (PMID 23316217, 2012). "Interestingly, recent studies have shown that PPARγ is expressed in normal and malignant human brain and that treatment with PPARγ agonists induces growth arrest and apoptosis in brain tumour cells in vitro and in animal models in vivo, but their effects on BTSCs are unknown." (PMID 19018263, 2008). "In this study, we show that PPARγ agonists inhibit growth and expansion of CD133+ BTSCs as gliospheres in culture, further suggesting its use in the treatment of brain tumour." (PMID 19018263, 2008). "PPARγ expression was increased almost 5-fold in metronomic CPA-treated U251 tumor cells, and this could contribute to the responsiveness of these brain tumors to metronomic CPA." (PMID 25952672, 2015).
Cachexia (11 papers, 2013 to 2025). Severe weight loss, wasting of muscle, loss of appetite, and general debility related to a chronic disease. "Furthermore, BC mediated cachexia is also associated with a decrease in adipogenesis transcription factors PPARγ, c/EBPα, GLUT4 and SREBP-1, and an increase in HSL, an enzyme responsible for lipolytic activity in cachexia." (PMID 32796696, 2020). "Peroxisome proliferator-activated receptor gamma (PPARγ) has emerged as a key regulator of adipogenesis, lipid metabolism, and inflammation, but its role in cachexia is paradoxical." (PMID 41476922, 2025). "Dietary omega-3 fatty acids, particularly eicosapentaenoic acid (EPA) and docosahexaenoic acid (DHA), can act as nutritional ligands for PPARγ and have been investigated in numerous cachexia studies." (PMID 41476922, 2025). "Accordingly, activation of PPARγ in cachexia models has been shown to attenuate cytokine-driven WAT browning, preserve lipid stores, and restore a more regulated, metabolically competent adipose phenotype." (PMID 41476922, 2025). "Collectively, the evidence identifies PPARγ as a central regulator of anti-catabolic signaling, crucial for preserving skeletal muscle integrity in cachexia." (PMID 41476922, 2025). "These multifaceted actions position PPARγ as a promising therapeutic target for alleviating the systemic inflammation and tissue catabolism that characterize cachexia." (PMID 41476922, 2025). "Understanding the crosstalk between PPARγ and other NRs is essential for deciphering its dualistic role in cachexia." (PMID 41476922, 2025). "In cachexia, chronic PPARγ activation and pioglitazone-induced AMPKα activation converge to suppress mTOR signaling, impair protein synthesis, and promote autophagy through altered energy metabolism (↑ glycolysis, ↑ FA oxidation, ↓ ATP)." (PMID 41476922, 2025). "Given the multifactorial nature of cachexia, encompassing muscle atrophy, lipolysis, anorexia, and chronic inflammation, PPARγ agonists offer a mechanistically diverse therapeutic strategy that targets several hallmarks of this syndrome." (PMID 41476922, 2025). "Emerging approaches in tissue-specific drug delivery provide additional opportunities to refine PPARγ-targeted therapy for cachexia." (PMID 41476922, 2025). "Evidence from tumor-bearing mouse models demonstrates that administration of the PPARγ agonist GW1929 (10 mg/kg body weight) significantly attenuates muscle wasting during experimental cachexia." (PMID 41476922, 2025). "It was found that both C/EBPα and PPARγ levels were inhibited by cachexia, but BGM recovered and substantially increased the expression levels of these two proteins." (PMID 33802674, 2021). "Emerging evidence also implicates PPARγ in skeletal muscle biology, where it contributes to muscle fiber type switching and suppresses myosteatosis, both of which are relevant to muscle wasting conditions such as cachexia." (PMID 41476922, 2025). "Although further research is needed to clarify the precise role of hypothalamic PPARγ in SNS-BAT axis regulation during cachexia, current evidence supports its function as a central neuroimmune-metabolic integrator and a promising target for therapeutic intervention." (PMID 41476922, 2025). "Direct evidence of hypothalamic PPARγ activity in cachexia is limited." (PMID 41476922, 2025). "Together, these findings reveal that while GR signaling is indispensable for the muscle catabolism observed in cancer cachexia, its interaction with PPARγ pathways in adipose tissue remodeling is more nuanced and may involve ligand-specific or tissue-specific regulatory mechanisms." (PMID 41476922, 2025). "In cachexia, insulin receptor, GH, and IGF-1 pathways; peroxisome proliferator-activated receptor gamma (PPARγ) agonists; angiotensin II inhibitors; and testosterone are possible therapeutic targets." (PMID 35565236, 2022).
Cachexia (continued). "Notably, activation of PPARγ has been shown to reduce phosphorylation of NF−κB and STAT3 both in vitro and in vivo, thereby disrupting the chronic inflammatory feedback loop that sustains cachexia progression." (PMID 41476922, 2025). "Several studies have found that the mRNA and protein levels of PPARγ decreased significantly in visceral adipose tissue during the process of cancer cachexia, demonstrating that the disorder of the PPARγ signaling pathway in lipid metabolism aggravated the development of cachexia." (PMID 34093209, 2021).
chondrosarcoma (11 papers, 2002 to 2024). A malignant cartilaginous matrix-producing mesenchymal neoplasm arising from the bone and soft tissue. "PPARγ activation has been shown to inhibit cell proliferation and induce apoptosis, with zaltoprofen demonstrating efficacy in activating PPARγ in chondrosarcoma cells." (PMID 39590345, 2024). "The ligand-activated transcription factor peroxisome proliferator-activated receptor gamma (PPARγ) has been reported as a candidate for a therapeutic target in malignant tumors, including chondrosarcomas." (PMID 35163019, 2022). "Peroxisome proliferator‐activated receptor gamma (PPARγ) is a ligand‐activated transcription factor, which has been reported as a possible therapeutic target in certain malignancies including chondrosarcomas." (PMID 29573200, 2018). "PPARγ silencing in chondrosarcoma cells, OUMS27shPPAR and SW1353shPPAR, exhibited a significant inhibition of cell migration even in the nontreated control and following cancelation of the inhibitory effect by zaltoprofen, as well as ARP100." (PMID 29573200, 2018). "The results are further supported by the ability of PPARγ to induce apoptosis in chondrosarcoma cells." (PMID 20182546, 2010). "The decreased expression of antiapoptoticBcl-xL in OUMS-27 treated by 15d-PGJ2 led us to examine the expression in thetissue of human chondrosarcoma samples to study the clinical application ofdifferentiation therapy by PPARγ activation." (PMID 18725985, 2008). "In vivo PPARγ proteincontent was examined in conventional chondrosarcoma specimens from 28 patientsundergoing surgery." (PMID 18725985, 2008). "The frequent expression of PPARγ in chondrosarcoma cells indicated the involvement of PPARγ in the pathogenesis of chondrosarcoma and suggested the possible inhibitory effect on cancer cell growth and proliferation by PPARγ activation." (PMID 11953889, 2002). "In the current study, the authors demonstrated for the first time that PPARγ is expressed in both surgically resected human chondrosarcoma and OUMS-27 cells." (PMID 11953889, 2002). "Activating peroxisome proliferator-activated receptor gamma (PPARγ) in chondrosarcoma cells—either directly or with drugs like zaltoprofen—has been shown to inhibit cell proliferation, induce apoptosis, and reduce invasion, marking it as a viable therapeutic pathway." (PMID 39590345, 2024). "In this study, we demonstrated that a nonsteroidal anti‐inflammatory drug, zaltoprofen, could induce PPARγ activation and elicit anti‐tumor effects in chondrosarcoma cells." (PMID 29573200, 2018). "Moreover, the downregulation of the EdU‐positive cell ratio by zaltoprofen was significantly inhibited by PPARγ silencing in chondrosarcoma cells, OUMS27shPPAR and SW1353shPPAR cells." (PMID 29573200, 2018). "In the present study, we found that zaltoprofen could dose‐dependently upregulate PPARγ activities and significantly, but mildly, induce PPARγ expression in human chondrosarcoma OUMS27 and SW1353 cells." (PMID 29573200, 2018). "The purpose of this study was to assess the anti‐tumor effects of zaltoprofen via regulation of MMP2 and PPARγ activity, and examine whether zaltoprofen could be a novel therapeutic agent in human chondrosarcoma." (PMID 29573200, 2018). "Moreover, zaltoprofen treatment dose‐dependently increased expression levels of PPARγ protein in both cell lines as observed by western blotting, indicating that zaltoprofen induces PPARγ expression in chondrosarcoma cells." (PMID 29573200, 2018). "The fusion protein EWSRI/NR4A3 in extraskeletal chondrosarcomas activates PPARγ expression." (PMID 20182546, 2010). "Immunohistochemical study revealed that human chondrosarcoma cellsfrequently express PPARγ protein." (PMID 18725985, 2008). "In conclusion, the current study showed that PPARγ activators induce apoptosis of human chondrosarcoma cells, suggesting that PPARγ activators might have potential therapeutic benefit in the treatment of chondrosarcoma." (PMID 11953889, 2002).
chondrosarcoma (continued). "Zaltoprofen was found to induce expressions of PPARγ mRNA and protein in human chondrosarcoma SW1353 and OUMS27 cells, and induce PPARγ‐responsible promoter reporter activities." (PMID 29573200, 2018). "In conclusion, this study showed that zaltoprofen activated PPARγ and subsequently decreased MMP2 activity in human chondrosarcoma cells, thereby contributing to anti‐tumor effects against cell viability, proliferation, migration, and invasion." (PMID 29573200, 2018). "Chondrosarcoma (malignant cartilage tumor) and OUMS-27 cells (cell line established from grade III human chondrosarcoma) express PPARγ." (PMID 18725985, 2008). "In chondrosarcoma, whether the celldeath and growth inhibitory effects induced by 15d-PGJ2 are PPARγ-dependent or -independent isunknown." (PMID 18725985, 2008). "In the current study, the first of its kind, the authors examined the expression of PPARγ both in surgically resected sections of human chondrosarcoma and OUMS-27 cells, a novel cell line established from a grade III human chondrosarcoma of a 65-year-old male." (PMID 11953889, 2002). "However, in OUMS27shPPAR and SW1353shPPAR cells, the downregulation of MMP2 activities by zaltoprofen was inhibited by PPARγ silencing, thus, suggesting that a zaltoprofen‐induced PPARγ activation could reduce MMP2 activities in chondrosarcoma cells." (PMID 29573200, 2018). "Specifically, we previously analyzed the anti-tumor effect of zaltoprofen, a nonsteroidal anti-inflammatory drug (NSAID), via peroxisome proliferator-activated receptor gamma (PPARγ) in some musculoskeletal tumors, including TGCT, giant cell tumor of bone and chondrosarcoma." (PMID 36212437, 2022).
emphysema (11 papers, 2012 to 2024). "Specifically, Solleti and colleagues have suggested that PPARG in the airway epithelial cell is able to modulate cigarette smoke-induced chemokine expression and emphysema susceptibility in mice." (PMID 38750544, 2024). "Despite the important functions of PPARγ in various cell types of the lung, PPARγ-deficiency in club cells induces only mild emphysema." (PMID 30212482, 2018). "Mice experiments have shown that activation of PPARG downregulates the expression of inflammatory chemokines and mitigates cigarette-smoking induced emphysema." (PMID 36672643, 2023). "Increasing evidence indicates that the nuclear hormone receptor PPARγ, a regulator of lipid metabolism, adipogenesis, and inflammation, represents a potential therapeutic target for emphysema." (PMID 35047522, 2021). "A specific PPARγ deletion in airway epithelium produced persistent enlargement of the airspaces in adult mice, which showed more severe emphysema symptoms and higher macrophage numbers after exposure to cigarette smoke than did mice carrying the PPARγ gene." (PMID 22761606, 2012). "Also, overexpression of dominant-negative PPARγ in murine ATII cells induced emphysema with increased inflammatory cytokines, MMPs, and accumulation of myeloid-derived suppressor cells (MDSCs) in the lungs and circulation system." (PMID 35047522, 2021). "In addition, PPARγ agonists also ameliorate elastase-induced emphysema in mice." (PMID 34021254, 2021). "Various nuclear receptor agonists were reported to control neutrophil accumulation and the expression of MMP-9, and agonists of PPARγ and LXR exerted some anti-neutrophilic inflammatory and protective effects in the development of emphysema in a murine model." (PMID 30606200, 2019).
esophageal adenocarcinoma (11 papers, 2010 to 2025). A malignant tumor with glandular differentiation arising predominantly from Barrett mucosa in the lower third of the esophagus. "PPARγ expression in the epithelium of Barrett's esophagus (BE) is elevated as compared to that in the normal esophageal squamous epithelium." (PMID 20885923, 2010). "Online database showed PPARγ could directly bind to the promoter region of ENO1 promoter and ChIP-seq data in esophageal adenocarcinoma showed prominent binding peaks of PPARγ on ENO1 promoter region." (PMID 37024456, 2023). "Importantly, in vivo experiments strongly suggest that a high-fat diet (HFD) promotes esophageal adenocarcinoma growth through activating PPARγ." (PMID 36077352, 2022). "Thus, the role of PPARγ remains controversial in esophageal SCC as well as esophageal adenocarcinoma, and further examinations is required to gain a better understanding of the role of PPARγ in esophageal tumors." (PMID 20885923, 2010). "In a murine esophageal adenocarcinoma model, the ELF3 super-enhancer was up-regulated by nuclear receptor transcription factor peroxisome proliferator activating receptor γ (PPARγ) which is induced by a high-fat diet." (PMID 41425714, 2025). "The esophageal adenocarcinoma-specific master regulator transcription factors (MRTFs) ELF3, KLF5, GATA6, and EHF activate PPARγ." (PMID 35954274, 2022). "PPARγ, in turn, enhances the synthesis of fatty acids, phospholipids, and sphingolipids and, in a positive feedback loop, induces MRTF expression, suggesting a pro-cancerogenic function in esophageal adenocarcinoma." (PMID 35954274, 2022).
experimental autoimmune encephalomyelitis (11 papers, 2008 to 2025). An autoimmune demyelinating disease of the central nervous system that is produced experimentally in animals by the injection of homogenized brain or spinal cord in Freund's adjuvant. "Previous studies also reported that the PPARγ agonist ciglitazone promotes the TGFβ-dependent conversion of naïve effector T cells into Tregs, whereas PPARγ deficiency increases the infiltration of Th17 cells into the central nervous system in experimental autoimmune encephalomyelitis." (PMID 37917548, 2023). "A PPARγ agonist ameliorates experimental autoimmune encephalomyelitis or human central nerve system demyelinating diseases in animal models." (PMID 28114934, 2017). "In addition to Th1-mediated inflammation, PPARγ activation has been reported to mitigate Th17 responses in the central nervous system of mice with experimental autoimmune encephalomyelitis." (PMID 36430269, 2022). "Although all PPARs ameliorate experimental autoimmune encephalomyelitis (EAE), recent evidence suggests that PPARα, PPARβ/δ agonists have less pronounced immunomodulatory effects and, along with PGC-1α, are not biomarkers of neuroinflammation in contrast to PPARγ." (PMID 30669473, 2019).
Hepatitis (11 papers, 2012 to 2024). Inflammation of the liver. "In contrast, Pioglitazone-induced PPARγ activation exacerbated D-galactosamine (GalN)/lipopolysaccharide (LPS) hepatitis associated with an increased production of TNFα by Kupffer cells and increased sensitivity of hepatocytes towards TNFα after in vivo Pioglitazone administration." (PMID 32260486, 2020). "Moreover, it has been reported that reduced liver injury after flavonoid treatment in the model of GalN/LPS hepatitis was associated with increased expression of PPARγ." (PMID 32260486, 2020). "Schisandrin B alleviated CCl4-induced liver inflammation and fibrosis by inhibiting macrophage polarization by targeting peroxisome proliferator-activated receptor gamma (PPARγ)." (PMID 36518510, 2022). "In this study, PPARγ ligands and PPARγ+/− mice were used to confirm the effects of PPARγ on the liver injury induced by Con A. Con A induces serious hepatitis in mice by activating T cells and triggering apoptosis." (PMID 23251143, 2012). "All these data confirm that 15d-PGJ2 activates PPARγ in ConA-induced hepatitis." (PMID 25120564, 2014). "This prompted us to investigate whether pharmacological activation of PPARγ can augment the anti-inflammatory function of different hepatic immune cells and whether this influences liver injury in the murine model of immune-mediated GalN/LPS-induced hepatitis." (PMID 32260486, 2020). "Most strikingly, we found that PPARγ activation by Pioglitazone administration did not reduce but rather exacerbated GalN/LPS hepatitis." (PMID 32260486, 2020).
lymphoma (11 papers, 2008 to 2025). A malignant (clonal) proliferation of B- lymphocytes or T- lymphocytes which involves the lymph nodes, bone marrow and/or extranodal sites. "Elevated expression of PPARγ increases expression of fatty acids to inhibit NK cell response and cell metabolism in invasive B-cell lymphoma, which leads to the functional adaptation of NK cells to fatty acid rich lymphoma." (PMID 37976136, 2023). "PPARγ activation contributes to the survival of T lymphoma cells by affecting cellular metabolism." (PMID 35279210, 2022). "Importantly, ROSI cotreatment increased PPARγ expression in mammary-derived lymphomas and carcinomas from PPARγ-WT and PPARγ-MG KO mice, but only specifically augmented BRCA1 in PPARγ-WTs." (PMID 25889730, 2015). "In addition to those solid tumors, the function of PPARG has been also studied in lymphoma." (PMID 37976136, 2023). "Surprisingly, 15d-PGJ2 maintained its antiproliferative effects on B cells regardless of the presence of DN PPARγ construct, suggesting PPARγ-independent actions of 15d-PGJ2 in lymphoma cells." (PMID 26713087, 2015).